IL10 (interleukin 10)
Diseases named in the same sentence as IL10 in open-access papers (continued):
Sharing a sentence is not in itself a finding about the gene and the disease.
eosinophilia (continued). "Furthermore, IL-10 treatment induces AHR to allergen together with suppression of eosinophilia, which are paradoxical responses, due to the role of eosinophil in induction of AHR." (PMID 32024540, 2020). "In addition, we were interested in validating in this cohort the known associations of S. mansoni with circulating IL-10, TNF and eosinophilia." (PMID 30453907, 2018). "Previous studies have shown that PGE2-induced EP4 receptor activation mitigates airway inflammation and IL-10 inhibits eosinophilia by suppressing Th2 cytokine production, which is in line with the anti-inflammatory effects of EPA-stimulated MSCs in HDM-challenge mice." (PMID 29881388, 2018). "Since we observed a consistent upregulation of IL-10 in the lungs of T. muris-infected C57BL/6 and Rag1−/− mice, we hypothesized that blocking IL-10 activity would restore susceptibility to eosinophilia in infected Rag1−/− mice after papain challenge." (PMID 26644379, 2016). "Previous studies have also demonstrated that eosinophilia occurs between the 5th and 7th weeks after exposure to the parasite and may be induced by Th2 cytokines, such as IL-4, IL-10, IL-13, IL-9, and especially IL-5." (PMID 23401741, 2013). "Increased IL-10 levels could explain the reported reductions in IL-4 and IL-5 as well as the inhibition of eosinophilia, since IL-10 has been shown to downregulate IL-4 and IL-5 expression by Th2 cells and reduce eosinophil survival." (PMID 22966222, 2012). "However, macrophages, the minor inflammatory cell recruited into asthmatic lung tissue, can produce IL-10 to suppress Th2 cytokine production and eosinophilia but augments airway reactivity." (PMID 22563373, 2012). "In current study, in vivo IL-10 gene delivery can efficiently suppress airway eosinophilia." (PMID 16677403, 2006). "However, in mice that received the same amount of IL-10 gene plasmid as above in pIL-10-med group, the severity of airway hyper- responsiveness (p = 0.0022) and eosinophilia (p = 0.026) was significantly decreased." (PMID 16677403, 2006). "Interestingly, and in line with increased levels of IL-5 and IL-10 in cultured splenocytes of M. vaccae NCTC 11659T-treated mice, which correlated with decreased lung eosinophilia, numbers of IL-10 producing Tregs were also elevated following M. vaccae NCTC 11659 treatment." (PMID 34884743, 2021). "SLIT reduced TNSS, TMS, VAS scores, IL‐4, IL‐17, eosinophilia percentage (EOS%), and specific immunoglobulin E (sIgE) levels, while increasing INF‐γ, IL‐10, and sIgG4." (PMID 39739782, 2025). "Compared to free IL-10, IL10-AMNP significantly reduced airway hyperresponsiveness and T-helper 2 (Th2)/Th17 cytokines and inhibited neutrophilia and eosinophilia recruitment into the airways of HDM-induced mouse models." (PMID 37275919, 2023). "Concurrently, Sema6d−/− mice showed significantly diminished eosinophilia and ILC2 numbers in bronchoalveolar lavage fluid (BALF) after challenge with IL-33, as well as elevated IL-10 and less IL-5 and IL-13 in BALF compared to WT mice." (PMID 37947634, 2023). "Namely, Plexin B1 deficiency leads to increases in BALF and lung tissue inflammation, eosinophilia, mucus production, and Th2 cytokines in BALF, but downregulates IL-10." (PMID 38259471, 2023). "Accordingly, we speculate that the immunosuppressive effects of IL-10 on cells that produce eosinophilic chemoattractants result in mitigated eosinophil recruitment under normal conditions, an effect that was lost in Rag1−/− mice resulting in exaggerated eosinophilia." (PMID 34326406, 2021). "A lower eosinophilia was detected in LPS-pretreated mice, along with an increase in phagocytes and regulatory cells (CD4+CD25+FOXP3+ and CD4+IL-10+), together with higher levels of IL-12 and TNFα." (PMID 32379832, 2020).
eosinophilia (continued). "In summary, we report for the first time that in utero and postnatal vitamin D deficiency, with concomitant inhaled allergen exposure in the neonatal period, results in increased airway eosinophilia and Th2 cells and reduced CD4+IL-10+ T regulatory cells." (PMID 24943330, 2014). "In contrast, eosinophilia in the OVA-infected group of the IL-10−/− B cell mice was restored and was similar to the OVA-uninfected IL-10−/− B cell group and significantly higher compared to the OVA-infected WT group." (PMID 22347409, 2012). "The result of our study has shown that administration of IL-10 plasmids in OVA-sensitized and challenged mice can decrease airway hyper-reactivity, including eosinophilia and neutrophilia." (PMID 16677403, 2006). "Progesterone, on the other hand, significantly increases the expression of IL-10, IL1-β, and TNF-α in the lungs, and augments the release of IL-4 by bone marrow cells, which may lead to eosinophilia." (PMID 21639909, 2011). "Indeed, IL-10 is required for the development of AHR and administration of IL-10 enhanced AHR, though it reduces eosinophilia." (PMID 16677403, 2006). "Also, it was found that IL-10 is a crucial mediator secreted by macrophages to reduce inflammation through the inhibition of eosinophilia, and MSC-derived NV have also been shown to reduce bacteria-induced pro-inflammatory cytokines through upregulation of IL-10." (PMID 36604658, 2023). "IL-10 knockout mice do not develop airway hyper responsiveness after allergen sensitization and challenge, despite a significant pulmonary inflammatory response that includes increased airway eosinophilia." (PMID 28670318, 2017). "In this study, depletion of T-regs, and not of IL-10, restored lung eosinophilia to control levels." (PMID 27635405, 2016). "The experiments with IL-10 KO mice showed that the regulatory cytokine IL-10 would not play a significant role in T. gondii modulation since diminished BAL eosinophilia and goblet cell hyperplasia was detected in OVA sensitized infected animals (TO) compared to allergic mice." (PMID 22952678, 2012). "Interestingly, in the PBS-infected group, eosinophilia was equally high, suggesting that IL-10-producing B cells were involved in controlling non-allergic inflammatory processes during natural infections as well." (PMID 22347409, 2012). "Importantly, the ability of B cells from infected mice to block allergic reactions was evident in both total cell numbers and eosinophilia irrespective of IL-10 competence." (PMID 20306466, 2010). "Importantly, after OVA-inhalation challenge, treatment with ISS-ODN-stimulated IL-10-/- OVA-Mφ did not suppress airway eosinophilia." (PMID 15538945, 2004).
visceral leishmaniasis (74 papers, 2005 to 2025). A severe form of leishmaniasis characterized by irregular bouts of fever, substantial weight loss, swelling of the spleen and liver, and anemia (which may be serious). "Nevertheless, although IL-10 has been described to be associated with T-regulatory cytokines as part of acquired immunity, it typically falls to very low levels after kala-azar is cured." (PMID 40732663, 2025). "On the other hand, patients from Bangladesh with kala-azar had lower levels of IL-12 associated with elevated levels of IL-8 and IL-10." (PMID 41003560, 2025). "For example, in mouse models for Listeria monocytogenes, Streptococcus pneumoniae and visceral leishmaniasis, NK cell-derived IL-10 was found to increase susceptibility to infection." (PMID 39355242, 2024). "From the results of DisGeNET, the hub genes IL10, IL6, CXCL8, CSF2, IFNG, IL1B, and TNF were causing Visceral Leishmaniasis; IL10, IL4, CXCL8, IFNG, IL1B and TNF found to cause Cutaneous Leishmaniasis and Urban Cutaneous Leishmaniasis." (PMID 36989283, 2023). "In contrast to resistance, the susceptibility in visceral leishmaniasis has been accompanied by elevation in the levels of IL-10, a cytokine with anti-inflammatory activity and suppressive effects on the Th1 immune response." (PMID 33681389, 2021). "Different from the tegumentary forms, visceral leishmaniasis is associated with a downmodulated immune response, in which IL-10 seems to play a critical role." (PMID 29358935, 2017). "In contrast, a modulatory immune response, characterized by the production of IL-10, is a hallmark of visceral leishmaniasis." (PMID 29358935, 2017). "Rather clinical studies implicate a strong role for IL-10 associated with the immunosuppressive nature of kala-azar." (PMID 26829554, 2016). "These IL-10-producing Th1 (Tr1) cells have also been identified in humans with visceral leishmaniasis (VL) caused by Leishmania donovani and African children with Plasmodium falciparum malaria." (PMID 26765224, 2016). "Earlier genetic studies in Sudan, Brazil and Iran have shown the role of IL10 polymorphisms in visceral leishmaniasis (VL), cutaneous leishmaniasis (CL) and post kala-azar dermal leishmaniasis (PKDL) respectively." (PMID 25941808, 2015). "IL-27 produced by CD14 positive monocytes was also reported to be associated increased numbers of IL-10-producing Th1 cells in blood from visceral leishmaniasis patients." (PMID 25352846, 2014). "In humans, cutaneous leishmaniasis, visceral leishmaniasis and post-kala-azar dermal leishmaniasis have been associated with increased levels of IL-10." (PMID 23825956, 2013). "Type 1 B cells (B-1) have also been implicated in susceptibility in experimental visceral leishmaniasis infection with increased IL-10 and it has been shown that Balb/XID mice (B-1 cell deficient) have lower serum IL-10 and less parasite load in the spleen compared to the control." (PMID 36579347, 2022). "Distribution of IL10 genotype and alleles in cases and controls of visceral leishmaniasis." (PMID 25941808, 2015). "Importantly, these IL-10-producing Th1 cells have been identified in humans with visceral leishmaniasis caused by L. donovani and African children with P. falciparum malaria." (PMID 25352846, 2014). "IL-10 is a critical regulatory cytokine involved in the pathogenesis of visceral leishmaniasis caused by Leishmania donovani and clinical and experimental data indicate that disease progression is associated with expanded numbers of CD4+ IFNγ+ T cells committed to IL-10 production." (PMID 22911108, 2012). "In contrast, in symptomatic cases coinfected with HIV and kala-azar, elevated serum levels of IL-6, IL-10, and IL-17A were identified compared to healthy and asymptomatic controls." (PMID 41003560, 2025). "In this context, pretreatment serum levels of interferon-gamma (IFN-γ), tumor necrosis factor-α (TNF-α), IL-4, IL-6, IL-8, IL-10, and IL-27 are elevated in Brazilian individuals with untreated kala-azar." (PMID 41003560, 2025).
visceral leishmaniasis (continued). "L. infantum, in turn, induces both pro-inflammatory IL-1β and regulatory IL-10, reflecting the complexity of visceral leishmaniasis." (PMID 41200163, 2025). "Whereas the whole blood assay is widely used to measure antigen-specific cytokines, such as IFNγ and IL-10 in patients with visceral leishmaniasis, little is known about this assay in CL patients." (PMID 39933183, 2025). "(2007) described a direct positive correlation between the levels of IL-10 found in PBMC supernatants of post-kala-azar dermal leishmaniasis patients from India and the gravity and extension of their cutaneous lesions." (PMID 38410517, 2024). "Previous researchers studied PBMCs from patients with visceral leishmaniasis and reported reduced NO production and higher expression of IL-10 and TGF-β." (PMID 36977142, 2023). "During visceral leishmaniasis, IL-10 plays a crucial role in the immunosuppressive phase of the disease: high levels of this cytokine have been detected in patients with VL." (PMID 37235324, 2023). "In a complementary way, the pathogenesis of visceral leishmaniasis is correlated with high serum levels of the immunosuppressive cytokine IL-10, which makes it possible to promote the growth of L. donovani amastigotes in human macrophages." (PMID 37235324, 2023). "In human patients suffering from visceral leishmaniasis, IL-10 is also suggested to operate as a double-edged sword." (PMID 35464430, 2022). "It has long been established that high levels of interleukin-10 (IL-10) in keratinocytes are a strong predictor of the development of post-kala-azar dermal leishmaniasis in patients treated for visceral leishmaniasis." (PMID 35745464, 2022). "It has been shown that T cells themselves can be a source of IL-10 during visceral leishmaniasis in an antigen-dependent manner, determining infection aftermath in mice." (PMID 36579347, 2022). "During L. donovani infection, leading to visceral leishmaniasis, depletion of IL-10 was also shown to induce increased production of IL-12 and IFNγ." (PMID 35464430, 2022). "Possibly, in this chronic model of visceral leishmaniasis, where the disease is fully manifested, both Lu and UA lose the ability to restrain IL-10 expression and/or production maintaining a small number of parasites in the spleen and liver of hamsters." (PMID 33681389, 2021). "Listeria monocytogenes (Lm) systemic infection and experimental visceral leishmaniasis are the two animal models that have shown a detrimental effect of IL-10 produced by NK cells on immune host resistance against the pathogen." (PMID 35053151, 2021). "In consonance with our results, the blocking of this signaling cascade with anti-IL-10 antibodies in PBMCs from human patients with visceral leishmaniasis using a method similar to that employed herein was also shown to result in lymphoproliferation." (PMID 33465107, 2021). "Positive correlations were observed between the cortisol levels and the gene expression of factors related to promoting visceral leishmaniasis, such as arginase, IL-10, TGF-β, IL-1β, and IL-6." (PMID 34813597, 2021). "Together, the data indicate that NK cells produce IL-10 at early stages of visceral leishmaniasis in mice and continue producing IL-10 at a higher concentration over the course of infection while migrating into granulomas in the liver of infected mice." (PMID 35053151, 2021). "IL-10 has been associated with the suppression of TH1 cytokines, skewing the immune response towards a TH2 immune response, especially in cases of human visceral leishmaniasis." (PMID 34651045, 2021). "In respect to the immunological response, it has been observed that in visceral leishmaniasis, parasites downregulate IFN-γ, a Th1 related cytokine, and in contrast upregulate IL-10, a T regulatory associated cytokine." (PMID 33092305, 2020).
visceral leishmaniasis (continued). "Some studies have shown significant levels of IFN-γ and low levels of IL-10 in response to HLA-I or HLA-II restricted epitopes derived from different Leishmania proteins, used alone or as pools, in cured CL or visceral leishmaniasis (VL) individuals." (PMID 32176691, 2020). "We chose to study a model of visceral leishmaniasis because Th1 cell–derived IL-10 has been previously shown to be a critical for protection and pathogen clearance but also a critical determinant of disease outcomes in humans." (PMID 32321759, 2020). "Traditionally, IFN-γ and IL-10 are considered as the two main cytokines which determine the outcome of visceral leishmaniasis." (PMID 30175073, 2018). "In a study of human visceral leishmaniasis, pro-inflammatory cytokines acting on splenic macrophages had the potential to upregulate IL-27, which in turn induced IL-21 to expand IL-10+CD4+CD25−Foxp3− T cells as a mechanism of positive feedback control." (PMID 29033934, 2017). "The immune response to visceral leishmaniasis involves polyclonal B cell activation as well as overproduction of interleukin-10 and hypergammaglobulinemia." (PMID 26161864, 2015). "Therapy with AmB induced elevated production of TNFα, IFNγ and IL-12 in splenocytes of treated mice, and PBMC of kala-azar patients with reduced IL-4, IL-10 and TGFβ production." (PMID 25884796, 2015). "In visceral leishmaniasis, Foxp3− T cells were found to be the predominant IL-10 producers in the spleen." (PMID 23555256, 2013). "Nonetheless, in BALB/c mice vaccinated with recombinant A2 protein or LRP plus saponin, the protection against cutaneous or visceral leishmaniasis have been also correlated with a decrease in Leishmania-specific IL-4 and IL-10 mediated response." (PMID 23573301, 2013). "In an experimental model of visceral leishmaniasis, also NK cells were recently shown to produce IL-10 at late stages of infection, thus reducing host resistance." (PMID 23825956, 2013). "Visceral leishmaniasis is also noted for the production of the immunoregulatory cytokine IL-10, and targeting of IL-10 signaling has been identified as a potential therapeutic strategy." (PMID 22911108, 2012). "Further, elevated levels of IL-10 in serum and enhanced levels of IL-10 mRNA expression in lesion tissue are a direct indication of severe visceral leishmaniasis in mice and humans." (PMID 21912560, 2012). "Both in human and mice, the severity of visceral leishmaniasis have been most closely associated with increased levels IL-10, where the ratio of IFN-γ : IL-10 is the important denominator for the protection." (PMID 22091408, 2011). "Treg have not been definitively been implicated as providing a key source of immune counter-regulation in either experimental or human visceral leishmaniasis, settings in which it is likely that IL-10 production by other T cells is more important." (PMID 21909452, 2011). "Moreover, it should be noted that IL‐10 and TGF‐β levels are increased and associated with disease progression in human and canine visceral leishmaniasis." (PMID 40799008, 2025). "Although another study on healthy adult individuals did not observe this difference, the present findings suggest that a sex-dependent IL-10 response in patients with kala-azar may actually exist." (PMID 40732663, 2025). "However, a study in Kenya showed lower levels of IFN-γ and high levels of IL-10 in patients with severe kala-azar." (PMID 41003560, 2025). "The correlation analysis also indicated that parasite load positively correlates with high levels of IL-10 in primary CL patients, corroborating previous works with visceral leishmaniasis, in which parasite survival could be benefited by IL-10 synthesis." (PMID 36017367, 2022). "High IL-10 levels are pivotal to parasite survival in visceral leishmaniasis (VL)." (PMID 36668925, 2022).